POLE2 (DNA polymerase epsilon 2, accessory subunit)
Diseases named in the same sentence as POLE2 in open-access papers (continued):
Sharing a sentence is not in itself a finding about the gene and the disease.
tumor (17 papers, 2011 to 2025). "Bioinformatic analysis and an immunohistochemistry staining assay confirmed that POLE2 was significantly up-regulated in tumor tissues and was associated with poor survival in BLCA patients." (PMID 38370377, 2024). "Subsequently, based on the Mann–Whitney U analysis, we clarified that high POLE2 expression was positively correlated with gender (male), advanced tumor stage and high risk of lymphatic metastasis by the Mann–Whitney U analysis." (PMID 32831648, 2020). "Immunohistochemistry of tumor tissues showed that low protein expression of POLE2 was correlated with low protein expression of Ki67." (PMID 39155507, 2024). "Based on previous studies and our results, we concluded that POLE2 promoted tumor progression of OS cells by maintaining the expression of CD44." (PMID 38627379, 2024). "Meanwhile, comprehensive bioinformatic analyses revealed that POLE2 was the most important PEG associated with BLCA progression and was up-regulated both in mRNA and protein levels in tumor tissues." (PMID 38370377, 2024). "The representative image of IHC staining indicated that the higher the pathological grade, the higher the expression of POLE2 in the tumor tissue." (PMID 35039475, 2022). "High expression of POLE2 predicts tumor deterioration and poor prognosis in patients with ESCC, suggesting that POLE2 is a potential therapeutic target for preventing or delaying the progression of ESCC." (PMID 35780178, 2022). "Firstly, we found that the mRNA expression of POLE2 in tumor samples (169 cases) was significantly higher compared with the normal samples (5 cases) from the Cancer Genome Atlas (TCGA) database." (PMID 35039475, 2022). "The latest report demonstrated that knockdown of POLE2 can inhibit the tumor progression of esophageal squamous cells." (PMID 35039475, 2022). "The xenograft mice tumor models were established to further verify the role of POLE2 in regulating GBM cells in vivo." (PMID 35039475, 2022). "The results of in vivo imaging verified that the fluorescent intensity was diminished in the xenograft of the shPOLE2 group compared with that in the shCtrl group, indicating that POLE2 played a pivotal role in tumorigenesis and tumor growth of ACHN cells." (PMID 33644060, 2021). "Then, Spearman’s rank correlation analysis showed that the expression of POLE2 was positively correlated with tumor grade, stage and pathological T indicating that the expression of POLE2 increased with the degree of tumor malignancy." (PMID 33644060, 2021). "In the present study, POLE2 was also high expressed in RCC and associated with tumor poor prognosis of RCC patients, which was confirmed in TCGA, ICGC, and clinical RCC specimens." (PMID 33644060, 2021). "The tumor removed from the mice more intuitively presented that the downregulation of POLE2 weakens tumor formation." (PMID 32831648, 2020). "Taken together, these results suggested that downregulation of the expression of POLE2 can reduce the ability of tumor formation in mice in vivo, which was consistent with the data in vitro." (PMID 32831648, 2020). "Generally and significantly higher expression levels of POLE2 were observed in tumor tissues compared with normal tissues (P < 0.001), indicating the potential involvement of POLE2 in the development and progression of ESCC." (PMID 32831648, 2020). "In vivo studies proved that POLE2 was positively correlated with ESCC tumor formation, which was consistent with the results in vitro." (PMID 32831648, 2020). "Comparing polymerase components across thirty-seven tumor types revealed a common subset with elevated transcriptional pattern typified by POLE2 and POLQ that included EXO1, MCM10, GINS2, CDT1, ORC6L, and BLM." (PMID 31857847, 2019). "Silencing of POLE2 leads to a remarkable diminution of tumor weight." (PMID 39155507, 2024). "Of note, a higher level of POLE2 was found in OS tissues with more advanced tumor grades." (PMID 38627379, 2024).
tumor (continued). "We explored the tumor-promoting functions of POLE2 in OS cell lines and a nude mouse model." (PMID 38627379, 2024). "Moreover, we found that the metastasis lesions exhibited higher POLE2 expression than the primary tumours." (PMID 38070189, 2024). "Moreover, knockdown of CD44 inhibited the tumor-promoting effects of POLE2 overexpression on OS cells." (PMID 38627379, 2024). "Moreover, POLE2 is dramatically up-regulated in CRC tumor tissues compared with normal controls according to the StarBase analysis." (PMID 39155507, 2024). "Importantly, we investigated the downstream regulatory mechanism of POLE2, and found that POLE2 inhibited the ubiquitination degradation of CD44 to promote tumor progression." (PMID 38627379, 2024). "Inhibition of POLE2 could increase tumor cells proliferation, migration as well as invasion through Wnt/β-catenin signaling pathway." (PMID 39155507, 2024). "The fluorescence intensity of tumors in shPOLE2 group was obviously weaker than that of shCtrl, which preliminarily indicated that the downregulation of POLE2 could reduce the ability of tumor formation." (PMID 35039475, 2022). "Silencing of POLE2 inhibited the growth, proliferation, and apoptosis of tumor cells in vitro." (PMID 35780178, 2022). "Close to half of the significant genes for intron SNVs each involved more than 10% of patients, including DNA polymerase epsilon 2, accessory subunit POLE2, a gene for which knockdown has shown anti-tumor activity in vitro, with intronic SNVs involving 155 patients." (PMID 33554123, 2021). "In addition, the results of bioluminescence imaging showed that the fluorescence intensity of tumor in shPOLE2 group was much weaker than that in shCtrl group, indicating that POLE2 knockdown inhibited tumor formation." (PMID 32831648, 2020). "Moreover, the high expression of POLE2 can predict the tumor deterioration and poor prognosis of ESCC patients." (PMID 32831648, 2020). "Finally, the polymerases DNA2 and POLE2 appeared to be deregulated in the telomere pathway in a large number of tumours." (PMID 28387377, 2017). "IHC staining analysis of mice tumor tissues showed that the signal intensity of Ki67 in shPOLE2 group was significantly weaker than that in control group, which further confirmed that POLE2 knockdown could inhibit the tumor formation." (PMID 35039475, 2022). "The findings showed that AHNAK, POLE2, SHMT2, NR2F1, and TFRC expression in tumor tissues was substantially higher than in normal tissues (P < 0.05)." (PMID 38103068, 2023). "In order to further clarify the expression level of POLE2 in GBM, we performed IHC staining analysis in normal brain tissue and tumor tissue in clinical GBM patients." (PMID 35039475, 2022). "The results showed that intracellular POLE2 was the most significantly downregulated gene, and deletion of POLE2 inhibited proliferation and colony formation in A549 and NCI-H1299 cells, thus inducing apoptosis of tumor cells." (PMID 35780178, 2022). "Mechanically, POLE2 knockdown promoted the ubiquitination as well as reduced the stability of Forkhead transcription factor (FOXM1), which is a known tumor promotor in GBM, through Aurora kinase A (AURKA)." (PMID 35039475, 2022). "A pattern of increased expression typified by POLE2 and POLQ was found for multiple replication factors over thirty-seven tumor types." (PMID 31857847, 2019). "A common pattern of increased expression for POLE2 and POLQ in LUAD were found across thirty-seven tumor types." (PMID 31857847, 2019). "In addition, we assessed the expression of molecules such as ANKRD22, GINS3, POLE2, PLEK2, FERMT1 and METTL14 in subcutaneous tumours and lung metastatic tissues." (PMID 39021049, 2024). "In vivo experiments revealed that POLE2 attenuated RCC tumorigenesis and tumor growth." (PMID 33644060, 2021).
tumor (continued). "In a re-analysis of those data, one prominentgene-expression feature included genes regulating the cell-cycle (e.g. CCNE1,CDK1, CDC25A), and involved in DNA replication(e.g. POLE2, MCM4, TK1) andchromosome dynamics (e.g. SMC4, CENPE), ostensiblyreflecting tumor cell proliferation levels." (PMID 21629784, 2011). "Therefore, in this study, we comprehensively investigated the POLE2 expression and its role and mechanism in RCC from the biological, cellular and animal levels, then clarified that POLE2 was a tumor-promoting gene of RCC, and high POLE2 expression indicated poor prognosis." (PMID 33644060, 2021). "In vivo experiments indicate that the absence of GINS4 can suppress tumor growth in HCC, increase the expression of GPX4, and decrease the levels of Ki67, while also reducing the activity of the POLE2/PI3K/AKT signaling pathway." (PMID 40386780, 2025). "Besides, we found that knockdown of POLE2 inhibited RCC cell proliferation, migration and promoted apoptosis in vitro, as well as had a negative effect on tumor occurrence and development in vivo, which was consistent with other research results." (PMID 33644060, 2021).
cancer (15 papers, 2017 to 2024). A tumor composed of atypical neoplastic, often pleomorphic cells that invade other tissues. "RFC2, CHEK1, PCNA, and POLE2 were also associated with worse overall survival in several types of cancer (Group A and D)." (PMID 34853396, 2021). "Gains of POLE2 can alter the protein function and contribute to cancer risk." (PMID 37628631, 2023). "There is therefore an indication that variants in POLE and POLE2 might be associated with susceptibility to multiple cancer types." (PMID 29641532, 2018). "POLE2, which potentially acts as a therapeutic target and prognostic factor, is overexpressed in a variety of cancers." (PMID 37240068, 2023). "POLE2 is involved in many cellular functions such as DNA replication and is highly expressed in a variety of cancers." (PMID 35173608, 2021). "Western blot analysis also showed that knockdown of POLE2 inhibited the expression levels of Cancer-related pathway proteins including p-Akt, CCND1, MAPK9, and PIK3CA." (PMID 33644060, 2021). "Western blot analysis also showed that knockdown of POLE2 inhibited the expression levels of cancer-related pathway proteins including p-Akt, CCND1, and PIK3CA, while the expression of MAPK9 was promoted." (PMID 33644060, 2021). "However, the molecular mechanisms of POLE2 on BLCA tumorigenesis are poorly understood, despite several studies that have recently shown different molecular regulation mechanisms of POLE2 in other cancers." (PMID 38370377, 2024). "Our findings suggested that the POLE2 gene was crucial for cell proliferation, but its exact function in regulating cancer cell stemness is yet unknown in BLCA." (PMID 38370377, 2024). "Firstly, the Cancer Genome Atlas (TCGA) database found that POLE2 was highly expressed in GBM." (PMID 35039475, 2022). "Thus, it is not supervising that POLE2 is associated with cancer progression as its essential role in DNA replication." (PMID 38370377, 2024). "However, targeting POLE2 to treat cancer is rarely reported." (PMID 32241274, 2020). "One study found that POLE2 regulates its downstream oncogene STC1, activates AKT phosphorylation, decreases HIF-1α expression levels, and promotes cancer cell proliferation." (PMID 37240068, 2023). "It was found that POLE2, GABARAPL1, PIK3R1, NDC80, and TPX2 play critical roles in the response and overall survival in cancer patients under PD-L1 inhibitor treatment." (PMID 37240068, 2023). "Taken together, inhibiting these genes from cluster 1 represents a promising therapeutic avenue in several types of cancer, especially focusing on the combined inhibition of CHEK1 and POLE2." (PMID 34853396, 2021). "Our second and third-ranked targets, POLE2 and HMMR have been proven to promote PDAC and various other cancer types." (PMID 32241274, 2020). "The mRNA expression levels of POLE2 in RCC cancer tissues and corresponding normal tissues of TCGA-KIRC and ICGC-RCC cohorts were investigated and the results pointed out that the expression of POLE2 in RCC tissues was significantly higher than that in normal tissues." (PMID 33644060, 2021).
infection (2 papers, 2020 to 2021). The state of being infected such as from the introduction of a foreign agent such as serum, vaccine, antigenic substance or organism. "Knocking down POLD2 impaired TYLCV DNA replication in local infection assays, whereas knocking down POLE2 enhanced viral accumulation both locally and systemically." (PMID 33986276, 2021). "Our data suggest that the accessory components (RFC2, RFC3, RFC5, PCNA), polymerases (POLD1, POLD2, POLD3, POLE, POLE2, POLE4), and ligase LIG1, were downregulated during infection, for which the downregulation of RFC5, POLD1, POLD2, POLD3, POLE, and LIG1 was CagA-related." (PMID 33339161, 2020).
POLE2 also shares sentences with these, for which no sentence is quoted: cervical cancer (3 papers); mantle cell lymphoma (2); bladder tumor (1); brain glioma (1); endometrial cancer (1); hairy cell leukemia (1); hepatocellular carcinoma (1); hereditary cancer syndrome (1); Hip dysplasia (1); HIV-1 infection (1); Intellectual disability (1); lymph node metastasis (1); lymphoma (1); melanoma (1); non-Hodgkin lymphoma (1); osteosarcoma (1); pancreatic adenocarcinoma (1).